ACER2 (alkaline ceramidase 2)
Diseases named in the same sentence as ACER2 in open-access papers (continued):
Sharing a sentence is not in itself a finding about the gene and the disease.
cancer (12 papers, 2016 to 2025). A tumor composed of atypical neoplastic, often pleomorphic cells that invade other tissues. "Several researches indicate that ACER2 is associated with proliferation, apoptosis, DNA damage response, and autophagy in diverse cancer cells." (PMID 33093451, 2020). "Beyond CDKN1A and TP53INP1, ACER2 also plays a critical role in the DNA damage response and multiple lines of evidence support its role as a tumor suppressor in cancer cells." (PMID 41345520, 2025). "ACER2-mediated sphingolipid signaling, particularly through the SphK/S1P pathway, influences cancer development by modulating immune responses, inflammation, and the balance between cell survival and death." (PMID 39650647, 2024). "These analyses identified several cancer-related genes, including Kif26a, Acer2, Serpine1, Nr1d2, Efnb2, and Chst11, to be affected by ECS exposure." (PMID 39273313, 2024). "In various cancer cell lines, ACER2 overexpression influences key processes such as cellular proliferation, DNA damage response, programmed cell death, and autophagy." (PMID 39650647, 2024). "The involvement of ACER2 in sphingolipid metabolism positions it as a promising therapeutic target in GI cancers, particularly in cancers where its expression is dysregulated." (PMID 39650647, 2024). "By modulating the balance between pro-apoptotic ceramide, pro-survival sphingosine, and S1P, ACER2 contributes to both the promotion and suppression of cancer progression, depending on the context of its expression and regulation." (PMID 39650647, 2024). "Subsequently, we systematically explored correlations between ACER2 with immunomodulators, anti-cancer immune cycles, tumor-infiltrating immune cells, immune checkpoints and the T-cell inflamed score (TIS) to further confirm its immunological role in BLCA TME." (PMID 36936425, 2023). "ACER2 negatively correlated with the several critical steps of the anti-cancer immune cycles especially including the release of cancer cell antigens, and immune cells recruiting." (PMID 36936425, 2023). "We performed pan-cancer analysis to illustrate the immunological role of ACER2, and screened cancer types which were impacted most by ACER2." (PMID 36936425, 2023). "In this study, we uncovered that ACER2 was a potential molecular biomarker to reflect the TME status in diverse cancers especially in BLCA, and contribute to the formation of non-inflamed TME in BLCA." (PMID 36936425, 2023). "The overexpression of ACER2 in multiple cancer cells regulated proliferation, DNA damage response, programmed cell death, and autophagy." (PMID 36936425, 2023). "Subsequently, four major steps in the anti-cancer immunity cycle were downregulated in the high ACER2 group, which included the release of cancer cell antigens, priming and activation, immune cells recruiting and killing of cancer cells." (PMID 36936425, 2023). "Elevated expression of TIM is involved in the Alkaline Ceramidase 2 (ACER2) metabolism essential for cancer cell survival and invasion by enhancing mitochondrial respiration." (PMID 35126099, 2021). "TUBA1C serves as a prognostic biomarker for a variety of cancers and ACER2 is a Golgi enzyme involved in regulating B1 integrin maturation and cell adhesion." (PMID 34685586, 2021). "To determine if DXR upregulated ACER2 through DNA damage, we determined if treatment with a different DNA damaging agent upregulated ACER2 in selected cancer cell lines." (PMID 26943039, 2016). "ACER2 plays a key role in SphK/S1P signaling-mediated colon inflammation and cancer development." (PMID 39650647, 2024). "Considering the effect in the cancer cell apoptosis and proliferation, ACER2 could be served as a potential molecular target for cancer treatment." (PMID 36936425, 2023). "Besides, ACER2 was observed to be a crucial biomarker, which contribute to the tumor growth, invasion, and migration in several cancers." (PMID 36936425, 2023).
cancer (continued). "Based on our current findings, further extensive studies on the function of ACER2 and sphingosine might provide a clue to develop a promising strategy for cancer therapy." (PMID 28294157, 2017). "Of note, dysregulation of ACER2 has been observed in several types of cancers." (PMID 28294157, 2017). "Besides, ACER2 was negatively correlated with a majority of common immune checkpoint inhibitors, which restrained the re-invigorating of tumor-cytotoxic T-cells that recognized and eradicated cancer cells." (PMID 36936425, 2023). "With these in mind, ACER2 might be a novel molecular target for cancer therapy." (PMID 28294157, 2017). "We discovered ACER2 was significantly expressed in the TC0 and IC0 groups, which existed the lowest PD-L1 expression in the immune cells and cancer cells, respectively." (PMID 36936425, 2023). "Based on these novel and important findings, we envision that ACER2 activation in combination with SPHK inhibition and ceramide induction represents a novel modality in cancer prevention and therapy." (PMID 26943039, 2016). "In summary, we discovered that ACER2 promoted the formation of non-inflamed TME in BLCA which was resistant to cancer immunotherapy." (PMID 36936425, 2023). "In addition, we performed ROC analysis to illustrate the accuracy of ACER2 in predicting BLCA molecular subtypes and explored the response to several cancer-related treatments." (PMID 36936425, 2023). "In this current study, we showed that treatment with the DNA damaging agent DXR or 5-FU upregulated ACER2 in many but not all cancer cell lines that we examined." (PMID 26943039, 2016). "Additionally, ACER2 levels show a negative correlation with several well-characterized immune checkpoint inhibitors, which may hinder the re-activation of tumor-specific cytotoxic T lymphocytes responsible for targeting and eliminating cancer cells." (PMID 39650647, 2024). "In the IMvigor210 cohort, ACER2 was also observed negative correlations with several critical steps of cancer immune cycles, thus the infiltration level of TILs in TME was downregulated when ACER2 high expressed." (PMID 36936425, 2023). "ACER2 can contribute to the formation of non-inflamed BLCA TME supported by its negative correlations with immunomodulators, anti-cancer immune cycles, tumor-infiltrating immune cells, immune checkpoints and the TIS." (PMID 36936425, 2023).
tumor (12 papers, 2013 to 2025). "This suggests a strong tumor-suppressive function of ACER2 in TNBC and its association with enhanced drug sensitivity." (PMID 41345520, 2025). "In further studies, SPHK2 inhibitor needs to be used to prove that S1P is responsible for the promotion of tumor growth and cell mitochondrial respiration caused by ACER2 overexpression." (PMID 33093451, 2020). "Future research focusing on the precise mechanisms by which ACER2 contributes to tumor progression and immune modulation will provide valuable insights into novel treatment strategies for GI cancers." (PMID 39650647, 2024). "Acer2 has been shown to promote tumor growth and angiogenesis via catalyzing the formation of sphingosine-1-phosphate precursor sphingosine." (PMID 39273313, 2024). "Of note, ACER2/SMPDL3B promoted ceramide hydrolysis as well as S1P production that induced tumor cell growth and migration." (PMID 36594091, 2023). "The relatively higher expression of ACER2 inhibited the killing of tumor cells by decreasing TILs in the TME." (PMID 36936425, 2023). "The qPCR analysis of Xiangya cohort revealed that ACER2 was significantly elevated in tumor tissues (p = 0.0086) compared with normal urothelium." (PMID 36936425, 2023). "In our study, we uncovered ACER2 was overexpressed in the tumor tissues and tumor cell lines of BLCA." (PMID 36936425, 2023). "In this study, we demonstrate that the decrease of tumor growth induced by TIM knockdown is dependent on the expression of ACER2." (PMID 33093451, 2020). "We previously found that ACER2 was upregulated in human tumor cells in response to various forms of stress including serum deprivation and treatment with the retinoid 4-N-hydroxyphenyl retinamide (4-HPR)." (PMID 26943039, 2016). "Of note, it has recently been suggested that sphinganine level increase resulting from hydrolysis of dihydroceramides by alkaline ceramidase 2 (ACER2) is the mechanism of 4-HPR-induced cytotoxicity in tumor cells." (PMID 24040340, 2013). "In addition, we found that a stronger tumor-suppressive signature is correlated with greater sensitivity to doxorubicin and epirubicin, linking ACER2’s role to drug response." (PMID 41345520, 2025). "Understanding the mechanisms by which ACER2 regulates tumor progression and immune modulation may open new avenues for targeted therapies in gastrointestinal malignancies." (PMID 39650647, 2024). "Likewise, tobacco smoke exposure of WT male mice resulted in two to threefold induced expression of tumor suppressors, notably Acer2, Lbh and Zbtb16, and are reported to inhibit tumor growth and to induce apoptosis in LC." (PMID 38245882, 2024). "Notably, ectopic expression of ACER2 exhibits a dual effect on tumor cell dynamics, promoting both proliferation and apoptosis." (PMID 39650647, 2024). "Moreover, they would also be partly explained by the dual role of ectopic ACER2 in tumor cell proliferation and death." (PMID 36936425, 2023). "ACER2 was highly expressed in a majority of human tumor tissues." (PMID 36936425, 2023). "Herein we demonstrate that DNA damage increases sphingosine levels in tumor cells by upregulating alkaline ceramidase 2 (ACER2) and that the upregulation of the ACER2/sphingosine pathway induces PCD in response to DNA damage by increasing the production of reactive oxygen species (ROS)." (PMID 26943039, 2016). "However, the immunological role of ACER2 in tumor microenvironment (TME) was rarely reported." (PMID 36936425, 2023). "Our analysis indicates that ACER2 expression is downregulated in TNBC tumor compared to healthy controls, suggesting its potential tumor-suppressive role." (PMID 41345520, 2025). "Taken together, we discovered the suppressive immunological role of ACER2 in TME, but precise effects of ACER2 on tumor growth and death were perhaps controlled by multiple factors." (PMID 36936425, 2023).
tumor (continued). "Furthermore, data from the DepMap database reveals that knocking out ACER2 increases cell growth in some TNBC cell lines, providing functional evidence for its tumor-suppressive function." (PMID 41345520, 2025). "Collectively, ACER2 contributed to the formation of non-inflamed TME in BLCA, hence ACER2 may also contribute to the tumor growth, invasion, metastasis in the BLCA." (PMID 36936425, 2023).
infection (2 papers, 2020 to 2022). The state of being infected such as from the introduction of a foreign agent such as serum, vaccine, antigenic substance or organism. "Our qRT-PCR data revealed that sphingolipid metabolic key genes encoding enzymes: Cers2, Gba2, Gla, Asah1, Asah2, Acer2, Acer3, Neu3, Sgpp1, and Sphk1 were robustly upregulated in mRNA levels by the infection of C. sinensis." (PMID 36339341, 2022). "Given the role of ACER2 in enabling viral entry into human cells, any change in ACER2 expression caused by exposure to tobacco smoke (and potentially other nicotine-containing products) may have implications for an individual’s susceptibility to infection." (PMID 32641924, 2020).
ACER2 also shares sentences with these, for which no sentence is quoted: adrenomyeloneuropathy (1 paper); colorectal cancer (1); dementia (1); emphysema (1); endothelial dysfunction (1); Insulin resistance (1); ischemia (1); ischemic stroke (1); leukemia (1); liver fibrosis (1); melanoma (1).